DPH3 (diphthamide biosynthesis 3)
Description:
Required for the first step of diphthamide biosynthesis, a post-translational modification of histidine which occurs in elongation factor 2. DPH1 and DPH2 transfer a 3-amino-3-carboxypropyl (ACP) group from S-adenosyl-L-methionine (SAM) to a histidine residue, the reaction is assisted by a reduction system comprising DPH3 and a NADH-dependent reductase. Acts as an electron donor to reduce the Fe-S cluster in DPH1-DPH2 keeping the [4Fe-4S] clusters in the active and reduced state. Restores iron to DPH1-DPH2 iron-sulfur clusters which have degraded from [4Fe-4S] to [3Fe-4S] by donating an iron atom to reform [4Fe-4S] clusters, in a manner dependent on the presence of elongation factor 2 and SAM. Associates with the elongator complex and is required for tRNA Wobble base modifications mediated by the elongator complex. The elongator complex is required for multiple tRNA modifications, including mcm5U (5-methoxycarbonylmethyl uridine), mcm5s 2U (5-methoxycarbonylmethyl-2-thiouridine), and ncm5U (5-carbamoylmethyl uridine).
Synonyms: DelGIP1; DESR1; ZCSL2; MGC20197; KTI11; DELGIP; DPH3A
Tractability: No criterion of Open Targets' tractability assessment is met for any kind of drug.
Gene: Protein-coding gene on chromosome 3 (16,257,061 to 16,264,982, reverse strand). Ensembl gene ENSG00000154813.
Subcellular location: Cytoplasm; Nucleus
Subcellular location (Human Protein Atlas): Nucleoplasm; Cytosol
Pathways (Reactome):
Metabolism of proteins: Synthesis of diphthamide-EEF2
Gene Ontology:
Molecular function: protein binding; ferrous iron binding; iron chaperone activity; metal ion binding
Biological process: negative regulation of protein secretion; positive regulation of binding; protein histidyl modification to diphthamide; tRNA wobble base 5-methoxycarbonylmethyl-2-thiouridinylation
Cellular component: cytoplasm; cytosol; nucleoplasm; nucleus; protein-containing complex
Genetic constraint (gnomAD): Loss-of-function variants: 7 observed, 9.07 expected, observed/expected ratio (o/e) 0.77, 90% interval 0.44 to 1.44. That is too few expected variants to judge how well the gene tolerates losing a copy. Missense variants: 93 observed, 97.24 expected, observed/expected ratio (o/e) 0.96, 90% interval 0.81 to 1.14. Synonymous variants: 35 observed, 35.22 expected, observed/expected ratio (o/e) 0.99, 90% interval 0.76 to 1.32.
Homologues: Orthologues: macaque DPH3 (100% identical), chimpanzee DPH3 (99% identical), guinea pig DPH3 (98% identical), rabbit DPH3 (98% identical), mouse Dph3 (96% identical), dog DPH3 (95% identical), pig DPH3 (95% identical), rat Dph3 (95% identical), zebrafish dph3 (72% identical).
Diseases named in the same sentence as DPH3 in open-access papers:
DPH3 is named in the same sentence as 19 diseases in open-access papers, as found by Europe PMC text mining. Sharing a sentence is not in itself a finding about the gene and the disease. The quoted sentences say what the papers report.
melanoma (10 papers, 2012 to 2023). A malignant, usually aggressive tumor composed of atypical, neoplastic melanocytes. "To further validate these findings in vitro, we then tested the supernatant from A07 and C032 melanoma cell lines that were found to carry the DPH3 C8T promoter mutation." (PMID 30312528, 2019). "Mutations in the bidirectional promoter region of DPH3-OXNAD1 (called DPH3 promoter) were first described in melanoma in two whole genome screenings for mutations in the regulatory regions of the genome." (PMID 29165358, 2017). "DPH3 promoter mutations are present in up to 16% of melanomas and silencing of DPH3 in mouse melanoma cells impairs metastasis." (PMID 28555368, 2017). "Based on initial exome sequencing of 21 melanomas, we report frequent somatic mutations in skin cancers in a bidirectional promoter of diphthamide biosynthesis 3 (DPH3) and oxidoreductase NAD-binding domain containing 1 (OXNAD1) genes." (PMID 26416425, 2015). "The analysis of the mutational data showed that in melanoma the DPH3 promoter mutations associated with presence of solar lentigines at tumor sites." (PMID 26416425, 2015). "The mutations in the DPH3 promoter were first reported in melanoma in a study based on genome wide search for mutations in the regulatory regions of the genome." (PMID 26416425, 2015). "The reported frequency of DPH3 mutations in melanoma from whole genome and exome sequencing data in the Cancer Genome Atlas (TCGA) approximated 16% (6/38) and 14% (25/176), respectively." (PMID 26416425, 2015). "The underlying molecular mechanism for Dph3-regulated melanoma metastasis is identified to be related to AKT signaling pathway." (PMID 23185508, 2012). "By comparison with somatic mutation data from 221 melanomas, we found that DPH3 hotspot mutations corresponded at base-level with sharply elevated CPD formation (17.2-fold relative naked DNA) upstream of the core ETS motif (CCTTCCT); indeed the strongest stimulatory effect observed in our dataset." (PMID 37169761, 2023). "Recently, mutations in the DPH3 promoter region have been found in 10% of melanomas." (PMID 30312528, 2019). "The reported frequency of DPH3 mutations in melanoma was 16% (6/38) and 29.4%." (PMID 29165358, 2017). "Follow up screening of 586 different skin lesions showed that the DPH3 promoter mutations were present in melanocytic nevi (2/114; 2%), melanoma (30/304; 10%), basal cell carcinoma of skin (BCC; 57/137; 42%) and squamous cell carcinoma of skin (SCC; 12/31; 39%)." (PMID 26416425, 2015). "The mutations in the DPH3 promoter tend to co-occur with TERT promoter mutations more frequently than expected by chance in melanoma (OR = 3.0, 95% CI 1.4 - 6.4, P = 0.006), BCC (OR = 3.4, 95% CI 1.5 - 7.6, P = 0.003) and SCC (OR = 4.3, 95% CI 0.9 - 20.2, P = 0.06)." (PMID 26416425, 2015). "Overexpression of DPH3 has been shown to promote migratory ability of murine melanoma and downregulation of its expression was shown to inhibit cellular invasion and metastasis in vivo." (PMID 32409749, 2020). "For example, patient MM475 had multiple recognized melanoma driver mutations including BRAF p.V600R, RAC1 p.P29S, MAP2K1 p.P124S, TERT C228T, and DPH3 C8T." (PMID 30312528, 2019). "DPH3 silencing impairs in vivo metastasis in mouse melanoma cells, and its family member DPH1, which is also required for diphthamide synthesis, has been attributed a tumor-suppressor role." (PMID 29165358, 2017). "More convincingly, Dph3 silencing markedly impaired the lung metastasis of murine melanoma B16F10 cells in vivo." (PMID 23185508, 2012). "As a result, we found that diphthamide synthesis 3 (Dph3) is involved in the cell migration of melanoma cells." (PMID 23185508, 2012). "In the present study, we identified a novel role for Dph3 in the metastasis of murine melanoma cells." (PMID 23185508, 2012). "In combination, these results strongly suggest that Dph3 facilitates the activation of AKT signaling pathway in B16F19 murine melanoma cells." (PMID 23185508, 2012).
melanoma (continued). "Further investigation with gene silencing of Dph3 showed that the metastasis of melanoma cells was significantly decreased as revealed by the wound healing assay and migration assay and this effect is specific to skin cancer cells." (PMID 23185508, 2012). "By silencing and overexpression of Dph3, we further confirmed the role of Dph3 in the migration of melanoma cells in vitro." (PMID 23185508, 2012). "We found that the metastasis of B16F10 murine melanoma cells was significantly inhibited, when the Dph3 gene was disrupted by insertional mutagenesis." (PMID 23185508, 2012). "Further investigation demonstrated that AKT signaling pathway is involved in Dph3-promoted melanoma migration and invasion." (PMID 23185508, 2012). "To conclude, these data indicate that AKT signaling is involved in Dph3 promoted metastasis of melanoma cells." (PMID 23185508, 2012). "Consistently, when Dph3 was silenced by siRNA in melanoma cells, AKT activation was also down regulated." (PMID 23185508, 2012). "The requirement of Dph3 in the migration of melanoma cells was further confirmed by gene silencing with siRNA in vitro." (PMID 23185508, 2012). "We found that Dph3 promotes the metastasis of murine melanoma cells in vitro and in vivo through the AKT signaling pathway." (PMID 23185508, 2012). "In the further work, it is worthwhile to elucidate the precise roles of Dph3 in regulating the AKT signaling thus mediating the metastasis in melanoma cells." (PMID 23185508, 2012). "In the present work, we reported the identification of a novel role of Dph3 whose disruption impaired the metastasis of murine melanoma B16F 10 cells." (PMID 23185508, 2012). "In the present study, we found that diphthamide synthesis 3 (Dph3) is involved in the metastasis of B16F10 murine melanoma cells by insertional mutagenesis." (PMID 23185508, 2012). "However, it is noteworthy that DPH3 over-expression was shown to promote cellular invasion and metastasis in murine melanoma cells in vivo, whereas silencing of DPH3 reduced development of metastasis." (PMID 31671846, 2019). "We did not observe a statistically significant difference in the DPH3 transcription levels based on the mutational status of the DPH3 promoter in melanoma, melanocytic nevi and BCC tumors." (PMID 26416425, 2015). "In particular, the non-coding mutations in the succinate dehydrogenase complex, subunit D, integral membrane protein (SDHD) and diphthamide biosynthesis 3 (DPH3) promoters have been shown to affect Ets binding motifs and occurred in melanoma at frequencies of 4-10 and 13%, respectively." (PMID 26416425, 2015). "All these data presented that Dph3 is involved in the metastasis of melanoma cells." (PMID 23185508, 2012). "Moreover, down regulation of Dph3 expression in B16F10 melanoma cells strikingly inhibits their cellular invasion and metastasis in vivo." (PMID 23185508, 2012). "Due to the important roles of Dph3 in the metastasis of melanoma B16F10 cells, it may serve as an attractive target for molecular targeting cancer therapy." (PMID 23185508, 2012). "We demonstrated that Dph3 disruption impairs the migration of B16F10 murine melanoma cells." (PMID 23185508, 2012). "Finally, we found that Dph3 promotes melanoma migration and invasion through the AKT signaling pathway." (PMID 23185508, 2012). "Taken together, these results indicated that silencing of Dph3 could reproduce the effect of Dph3 disruption by pDisrup 8 plasmid and drastically reduced the cell motility of melanoma cells." (PMID 23185508, 2012). "Moreover, reduction of Dph3 expression in melanoma B16F10 cells significantly impaired their metastasis in vivo." (PMID 23185508, 2012). "In this work, we firstly reported a novel role for Dph3 in the metastasis of melanoma cells." (PMID 23185508, 2012). "Collectively, these results suggest that Dph3 promotes motility of melanoma cells." (PMID 23185508, 2012).
melanoma (continued). "To determine whether Dph3 is widely expressed in melanoma cells, we examined the expression of Dph3 in various human melanoma cells (M102, SK-28, and 888-mel)." (PMID 23185508, 2012). "However, the specificity and high recurrence of the mutations in the DPH3 promoter, particularly in BCC and SCC and findings from an earlier report in melanoma, merits further investigations for determining the functionality and relevance of those mutations in the process of carcinogenesis." (PMID 26416425, 2015). "However, it may be pointed out that over-expression of Dph3 promotes the migratory ability of murine melanoma cells, whereas down regulation of Dph3 expression inhibited cellular invasion and metastasis in vivo." (PMID 26416425, 2015). "However, the detail mechanisms underlying Dph3 regulating the metastasis of melanoma cells is till not clear." (PMID 23185508, 2012). "To perform this experiment, we first silenced the expression of Dph3 in melanoma B16F10 and B16F0 cells with a siRNA-incorporated plasmid targeting a specific site of mouse Dph3 mRNA." (PMID 23185508, 2012). "In contrast, the overexpression of Dph3 in murine B16F10 and B16F0 melanoma cells greatly enhanced the migration of melanoma cells." (PMID 23185508, 2012). "To further confirm the role of Dph3 in melanoma motility, we cloned Dph3 into pIRES-EGFP vector and transfected it into melanoma B16F10 and F0 cells." (PMID 23185508, 2012). "Our results showed that overexpression of Dph3 in B16F10 murine melanoma cells induces upregulation of AKT phosphorylation and Dph3 silencing leads to reduced AKT phosphorylation." (PMID 23185508, 2012). "In corresponding to this result, overexpression of Dph3 significantly promoted the migratory ability of B16F10 and B16F0 melanoma cells." (PMID 23185508, 2012). "As expected, we found that Dph3 is highly expressed in examined human melanoma cells (data not shown), especially in M102 cell line." (PMID 23185508, 2012).
skin cancer (5 papers, 2012 to 2023). "Of note, emerging reports are showing that somatic, non–coding mutations within promoter regions of TERT and DPH3-OXNAD1 genes are common in all types of skin cancer, including BCC." (PMID 29165358, 2017). "In this communication we report frequent somatic mutations within a bidirectional promoter region of DPH3 and OXNAD1 genes in three major types of skin cancers." (PMID 26416425, 2015). "While TERT promoter mutations are frequent in many cancers, we did not observe the DPH3 mutations in three non-skin cancers that were screened in this study." (PMID 26416425, 2015). "The results from this study show occurrence of frequent somatic non-coding mutations adjacent to a pre-existing binding site for Ets transcription factors within the directional promoter of DPH3 and OXNAD1 genes in three major skin cancers." (PMID 26416425, 2015).
ovarian carcinoma (2 papers, 2012 to 2013). A malignant neoplasm originating from the surface ovarian epithelium. "Interestingly, compared to the pro-metastatic effect of Dph3, Dph1, which deletion in mouse leads to embryonic lethality as Dph3, was reported as a tumor suppressor gene for breast and ovarian cancer." (PMID 23185508, 2012).
Alzheimer disease (1 paper, 2025). A progressive, neurodegenerative disease characterized by loss of function and death of nerve cells in several areas of the brain leading to loss of cognitive function such as memory and language. "The analysis based on the SC2disease database also indicates that Dph3 and Nbr1 are associated with Alzheimer's disease." (PMID 39912396, 2025).
bladder tumors (1 paper, 2015). "We also screened DNA from bladder tumors (n = 70), gliomas (n = 70) and squamous cell carcinoma of esophagus (n = 22) and none harbored DPH3 promoter alterations." (PMID 26416425, 2015).
cancer (6 papers, 2012 to 2021). A tumor composed of atypical neoplastic, often pleomorphic cells that invade other tissues. "With such features, it would otherwise be expected that the DPH3-proximal mutations would be prime candidates to be a potential driver in cancer development." (PMID 26356674, 2015). "Aged sun exposed normal skin has been shown to contain clones with various cancer associated mutations; however, in our study we could detect DPH3 promoter mutations unambiguously in tumors but not in the surrounding skin." (PMID 26416425, 2015). "So far, no investigation has been carried out on the involvement of Dph3 in cancer." (PMID 23185508, 2012).
tumor (6 papers, 2012 to 2021). "Inactivation of DPH3 is characterized by loss of a tumor cell’s metastatic ability, and therefore the gene has a tumor suppressor activity." (PMID 34359772, 2021). "The reason why Dph1 and Dph3 function so differently in tumor cells needs to be further investigated." (PMID 23185508, 2012).
neurological diseases (1 paper, 2025). "The SC2disease database was used to analyze the association of Nbr1 and Dph3 with neurological diseases." (PMID 39912396, 2025). "Dph3 and Nbr1 are closely related to neural development and neurological diseases." (PMID 39912396, 2025).
DPH3 also shares sentences with these, for which no sentence is quoted: basal cell carcinoma (2 papers); basal cell carcinoma of skin (1); carcinomas of skin (1); colon cancer (1); glioma (1); Merkel Cell Carcinoma (1); Miller-Dieker syndrome (1); non-melanoma skin carcinoma (1); squamous cell carcinoma (1); squamous cell carcinoma of esophagus (1); squamous cell carcinoma of skin (1).